KL (klotho)
Diseases named in the same sentence as KL in open-access papers (continued):
Sharing a sentence is not in itself a finding about the gene and the disease.
epilepsy (3 papers, 2021 to 2025). A brain disorder characterized by episodes of abnormally increased neuronal discharge resulting in transient episodes of sensory or motor neurological dysfunction, or psychic dysfunction. "Quantitative real-time PCR (qRT-PCR) was performed to assess Klotho and epilepsy-associated gene expression (STAT3, Bax, Bcl2)." (PMID 40351444, 2025). "In epilepsy, Klotho has been linked to seizure susceptibility and neuronal survival." (PMID 40351444, 2025). "Due to its neuroprotective, anti-inflammatory, and antioxidant properties, Klotho activation has been proposed as a potential therapeutic strategy for epilepsy and other neurodegenerative conditions." (PMID 40351444, 2025). "The study also emphasizes the role of Klotho as a promising therapeutic target in epilepsy due to its multifaceted regulatory functions in metabolic, inflammatory, and oxidative stress pathways." (PMID 40351444, 2025). "By elucidating the mechanistic crosstalk between Klotho and these pathways, this research opens new avenues for developing innovative strategies to address the challenges of epilepsy and its comorbidities." (PMID 40351444, 2025). "The current study focuses on the synthesis and biological evaluation of pyrroloquinoline and pyrroloindoline-based molecules for their potential effects on Klotho protein activation and neuroprotection in epilepsy models." (PMID 40351444, 2025). "This study investigates the therapeutic potential of novel physostigmine analogues in regulating Klotho expression and its downstream targets in epilepsy." (PMID 40351444, 2025). "Klotho, a neuroprotective, anti-inflammatory, and antioxidative protein has emerged as a potential modulator of epilepsy-related pathways." (PMID 40351444, 2025). "The therapeutic potential of 1,8-bis(phenylsulfonyl)-1,8-dihydropyrrolo [2,3-b] indole in epilepsy via Klotho modulation was observed." (PMID 40351444, 2025). "The authors experimented with the pentylenetetrazol (PTZ)-induced kindling animal model and affirmed that CUR significantly protected against epilepsy via upregulation of klotho and erythropoietin (EPO), as well as via the reduction of neuronal cell death." (PMID 36678859, 2023). "Furthermore, the hub genes of AD- and epilepsy-associated GCMs were captured by weighted key driver analysis (wKDA), including TRPC1, C2ORF40, NR3C1, KIAA0368, MMT00043109, STEAP1, MSX1, KL, and CLIC6." (PMID 34697589, 2021). "Furthermore, the hub genes of each AD- and epilepsy-associated GCM were captured, including TRPC1, C2ORF40, NR3C1, KIAA0368, MMT00043109, STEAP1, MSX1, KL, and CLIC6." (PMID 34697589, 2021).
esophageal cancer (3 papers, 2023 to 2024). A primary or metastatic malignant neoplasm involving the esophagus. "The use of Klotho levels as diagnostic markers was less frequently observed in the literature, although one study provided detailed data regarding soluble αKlotho levels in blood serum and the diagnosis of esophageal cancer." (PMID 37958253, 2023).
Hypercholesterolemia (3 papers, 2022 to 2024). An increased concentration of cholesterol in the blood. "In the present study, we analyzed rabbit myocardial specimens to better understand the transcriptional dynamics of proatherogenic cytokines, pivotal stem cell genes, and the response of klotho in the context of hypercholesterolemia." (PMID 38610757, 2024). "Lastly, our study was not equipped to explore the precise pathways through which hypercholesterolemia and statins affect cytokine, stem cell gene, and klotho expression." (PMID 38610757, 2024).
hyperuricemia (3 papers, 2022). An abnormally high level of uric acid. "This study investigated the association between hyperuricemia and serum klotho protein levels in a representative sample of adults in the United States." (PMID 35351833, 2022). "We also assumed that low levels of circulating klotho are associated with elevated uric acid levels or hyperuricemia." (PMID 35351833, 2022). "Most importantly, the inverse association of klotho with the presence of hyperuricemia and gout history was evident." (PMID 35351833, 2022). "Although further research is needed to clarify the biological mechanism of the observed association, this finding suggests that circulating klotho levels may be involved in the progression of hyperuricemia or subsequent gout." (PMID 35351833, 2022). "The results of this study suggest that loss of klotho may be involved in the progression of hyperuricemia." (PMID 35351833, 2022). "Accordingly, the occurrence of hyperuricaemia and low s-Klotho levels in women should be noted in clinical practice as it may indicate a hidden crisis." (PMID 35603960, 2022). "Compared with subjects without hyperuricemia, those with hyperuricemia had significantly lower serum klotho levels (adjusted beta = −0.062; p < 0.0001)." (PMID 35351833, 2022).
hypogonadism (3 papers, 2013 to 2022). A disorder characterized by decreased function of the gonads. "Also, the AAS-induced hypogonadism as reflected by LH and FSH repression correlated to klotho levels." (PMID 35434614, 2022).
IgA nephropathy (3 papers, 2019 to 2022). "Last, KLOTHO expression is associated with markers of oxidative stress and miR-200c in renal biopsy samples from IgA nephropathy patients." (PMID 31199854, 2019). "In contrast, klotho expression in renal tissue affected by IgA nephropathy decreased as its histopathological severity progressed." (PMID 35099688, 2022). "To evaluate the link between oxidative stress and KLOTHO expression in human kidneys with IgA nephropathy, we performed immunohistochemical staining for KLOTHO." (PMID 31199854, 2019). "In this study, we show that klotho deficiency intensifies hypoxia-induced expression of IFN-α/β through the upregulation of RIG-I in kidneys, and that the expression of RIG-I is associated with that of IFN-α/β in actual patients with IgA nephropathy." (PMID 34673800, 2021). "In renal biopsy specimens of patients with IgA nephropathy, miR-200c was mainly detected by ISH in distal tubules, where KLOTHO is also expressed." (PMID 31199854, 2019).
interstitial lung disease (3 papers, 2022 to 2025). A diverse group of lung diseases that affect the lung parenchyma. "Klotho has previously been implicated in lung disease with effects on muco-ciliary clearance, airway inflammation, recovery from acute lung injury and interstitial lung disease amongst others." (PMID 36220392, 2022). "Additionally, Klotho may also play a significant role in the development of interstitial lung diseases, obstructive sleep apnea, and lung tumors." (PMID 38287280, 2024).
intervertebral disc degeneration (3 papers, 2012 to 2025). "Consistently, Klotho knockdown by RNA interferences largely diminished the anti-inflammatory and intervertebral disc protective effects in an Intervertebral Disc Degeneration (IDD) model." (PMID 32256598, 2020). "We focused on the effects of expression changes of Klotho protein during intervertebral disc degeneration to elucidate the molecular mechanisms of intervertebral disc degeneration." (PMID 32256598, 2020). "Therefore, the purpose of this study is twofold: to determine Klotho expression in nucleus pulposus cells and to determine the relationship between Klotho expression and inflammatory response during intervertebral disc degeneration." (PMID 32256598, 2020). "Moreover, it is necessary to examine whether, in nucleus pulposus cells, Klotho affects the activity of several signaling pathways, including those of TGF, FGF, or the MMP family, which may participate in intervertebral disc degeneration." (PMID 22551380, 2012).
iron deficiency (3 papers, 2022 to 2025). "Therefore, FGF23 antagonists are strong candidates for the treatment of renal anemia, iron deficiency and associated inflammation, and have the potential to attenuate Klotho deficiency." (PMID 35813388, 2022). "In the present study, we sought to investigate whether Klotho deficiency contributes to the development of renal anemia and iron deficiency and whether administration of Klotho can improve these conditions." (PMID 35813388, 2022). "Furthermore, Klotho administration did not improve iron deficiency in CKD mice but it decreased intestinal absorption of iron in control mice leading to reduced serum iron and transferrin saturation levels." (PMID 35813388, 2022).
liver cirrhosis (3 papers, 2013 to 2023). "We conclude that Klotho is increased in liver cirrhosis, being related to the TNF-α, lipid peroxidation, and especially to liver function impairment." (PMID 36009045, 2022). "The hypothetical reactive increase of Klotho in liver cirrhosis may explain the counterintuitive relationship of Klotho with survival that is especially marked in cirrhotics." (PMID 36009045, 2022). "Some investigations found that non-cirrhotic alcoholics had much lower klotho levels than controls but significantly higher in liver cirrhosis." (PMID 37784055, 2023). "Based on this reasoning, the aim of the present study is to analyze the relationship of Klotho with proinflammatory cytokines (TNF-α, IL-6, and IL-8) and the lipid peroxidation products (Malondialdhyde = MDA) among alcoholics with or without liver cirrhosis, and its relationship with survival." (PMID 36009045, 2022).
malnutrition (3 papers, 2016 to 2021). Inadequate nutrition resulting from poor diet, malabsorption, or abnormal nutrient distribution. "The results of previous studies performed at our center have indicated that abnormal FGF23, klotho, and fetuin-A levels and malnutrition represent risk factors for abdominal aortic calcification in patients with ESRD." (PMID 34759797, 2021). "Our previous work identified abnormal FGF23 and Klotho levels, inflammatory status, and malnutrition were the unconventional risk factors for vascular calcification and CKD-MBD in patients with end-stage renal failure." (PMID 34759797, 2021). "In recent years, the influence of nontraditional risk factors, such as FGF23, klotho abnormality, microinflammatory state, and malnutrition on vascular calcification has attracted much attention from scholars." (PMID 34367315, 2021).
Multiple Organ Failure (3 papers, 2017 to 2022). A progressive condition usually characterized by combined failure of several organs such as the lungs, liver, kidney, along with some clotting mechanisms, usually postinjury or postoperative. "In 1997, the antiaging protein klotho was discovered when unanticipated silencing of the Klotho gene occurred in mice leading to multiple organ failure and shortened life resembling premature aging in human." (PMID 35951373, 2022). "Klotho (KL) is originally identified by an accidental site defect, which is related to premature multiple organ failure." (PMID 32571212, 2020).
neuroblastoma (3 papers, 2021 to 2024). Neuroblastoma (NB) is the most common solid, extracranial childhood tumor. "Recently, recombinant soluble klotho was found to protect SH-SY5Y human neuroblastoma cells against amyloid-β toxicity through decreasing reactive oxygen species and increasing superoxide dismutase activity." (PMID 34194816, 2021). "To this aim, we established a pull-down assay in which we incubated a lysate of SH-SY5Y human neuroblastoma cells with a biotinylated sequence of the shortest tRF upregulated in Klotho KO, tDR-36:74-Asn-GTT-2-M2, representing the shared sequence between the three upregulated fragments." (PMID 38862813, 2024).
obstructive sleep apnea (3 papers, 2019 to 2023). "Among individuals with obstructive sleep apnea, four single genetic variants (SNPs) of the klotho gene significantly mediated the association between obstructive sleep apnea and short leukocyte telomere length." (PMID 37580799, 2023). "In this regard, three recent papers report reduced levels of klotho or SIRT6 in obstructive sleep apnea or in patients with interstitial lung abnormalities." (PMID 34958949, 2022). "However, a very recent work has shown that patients with obstructive sleep apnea present lower plasma levels of Klotho as compared with healthy control volunteers." (PMID 31542779, 2019).
periodontitis (3 papers, 2022 to 2026). An acute or chronic inflammatory process that affects the tissues that surround and support the teeth. "The targeted modulation of Klotho holds promise as a novel strategy for the repair of alveolar bone defects and the prevention of periodontitis-related bone loss." (PMID 40427517, 2025). "Subsequently, the effect of Klotho overexpression on hPDLSC osteogenesis was evaluated under in vitro inflammatory environment and in vivo periodontitis model of C57BL/6 mice." (PMID 41540434, 2026). "Recent investigations have implied that Klotho is involved in the pathogenesis of various oral and maxillofacial diseases, including periodontitis, periapical periodontitis, oral submucous fibrosis, and oral and maxillofacial malignancies." (PMID 40427517, 2025). "Collectively, these mechanisms indicate that Klotho confers multiple protective effects in periodontitis, including anti-inflammatory, antioxidant, and anti-apoptotic actions." (PMID 40427517, 2025). "In periodontitis, Klotho has been reported to exert anti-inflammatory effects by activating the Nrf2 signaling pathway while concurrently inhibiting the NF-κB pathway." (PMID 40427517, 2025). "A cross-sectional study conducted in China showed that compared with those in the healthy counterparts, the levels of klotho in the gingival crevicular fluid and gingival tissues of chronic periodontitis patients were significantly lower." (PMID 36204099, 2022). "In vivo, injection of hPDLSCs-ov-KL could effectively promote periodontal tissue repair in the mouse model of periodontitis." (PMID 41540434, 2026). "For example, interventions targeting the Klotho-Nrf2 pathway could potentially slow the chronic progression of periodontitis, while regulating the interaction between Klotho and the Wnt/β-catenin pathway may offer novel approaches for oral cancer treatment." (PMID 40427517, 2025). "Linear dose-response relationships were found between serum α-klotho and the odds of moderate/severe periodontitis (P for non-linearity =0.88) and poor-rated oral health (P for non-linearity =0.66)." (PMID 36204099, 2022).
pituitary adenoma (3 papers, 2014 to 2021). "Recent data suggest that S-Klotho level is also elevated in patients with active acromegaly and that S-Klotho level decreases toward normal following removal of the GH-producing pituitary adenoma." (PMID 24692508, 2014). "Recent data suggest that S-Klotho level is dramatically elevated in patients with active acromegaly and decreases toward normal following removal of the GH-producing pituitary adenoma." (PMID 24692508, 2014). "Klotho is expressed in pituitary adenomas and its expression is higher in non-GH-secreting adenomas than in GH-secreting adenomas, suggesting that non-GH-secreting pituitary cells are capable of producing klotho." (PMID 33776931, 2021).
polycystic kidney disease (3 papers, 2021 to 2024). A usually autosomal dominant and less frequently autosomal recessive genetic disorder characterized by the presence of numerous cysts in the kidneys leading to end-stage renal failure. "A low-calorie, high-protein diet increases klotho levels in a rat’s brain, while a phosphate-restricted diet improves klotho kidney expression in a mouse model of polycystic kidney disease." (PMID 37999253, 2023). "Recent studies found that the whole-diet interventions are also effective to intensify Klotho function, with a low-calorie high-protein diet increased Klotho levels in rats' brain, while a phosphate-restricted diet improved kidney klotho expression in a mouse model of polycystic kidney disease." (PMID 35004821, 2021). "Notably, in one study utilizing the Han:SPRD (cy/+) rat model and an inducible PKD1 animal model of polycystic kidney disease (PKD), FGF-23 levels were increased, while tissue levels of Klotho did not exhibit any significant differences." (PMID 37985930, 2024).
renovascular hypertension (3 papers, 2021 to 2023). High blood pressure secondary to renal artery stenosis. "Four and sixteen weeks after the induction of renovascular hypertension by clipping the left renal artery, systemic blood pressure, serum angiotensin II level, and the expression of Klotho and SIRT1 proteins and oxidative stress indices in the heart and kidneys were assessed." (PMID 34730891, 2021).
scleroderma (3 papers, 2017 to 2018). Scleroderma is a rare autoimmune connective tissue disorder characterized by abnormal hardening of the skin and, sometimes, other organs. "The decreased serum Klotho, 25-OH Vit D, and increased iPTH levels in the scleroderma patients may be associated with the pathogenesis of this disease and could be considered a future therapeutic target." (PMID 28540270, 2017). "Serum Klotho and 25-OH Vit D concentrations were significantly lower in the scleroderma patients than those in the control group: [3.47 (2.30–11.07) vs. 4.28 (2.99–7.88), ng/mL; P<0.001] and [15.01±4.71 vs. 27.23±8.66, ng/mL; P<0.001], respectively." (PMID 28540270, 2017). "Serum levels of Klotho and 25-OH Vit D in the scleroderma patients were lower than those in the healthy controls (P<0.001)." (PMID 28540270, 2017). "In the present study, we evaluated some of the main factors involved in calcium and phosphate homeostasis including serum FGF-23, Klotho, vitamin D, and iPTH levels in the scleroderma patients compared with the healthy individuals." (PMID 28540270, 2017). "Serum Klotho and 25-OH Vit D levels were declined, but iPTH serum levels were increased in scleroderma disease." (PMID 28540270, 2017). "Some weaknesses of our study were no measurement of bone density and the possible effects of consumed drugs in the scleroderma patients on Klotho, vitamin D, iPTH, as well as FGF-23 levels." (PMID 28540270, 2017). "According to the results, scleroderma patients had significantly lower serum Klotho concentration than the controls." (PMID 28540270, 2017). "Low levels of Klotho in the scleroderma patients in our study might be due to the systemic inflammation and increased inflammatory markers in the diseases." (PMID 28540270, 2017). "According to the important roles of vitamin D, FGF-23, as well as Klotho in calcium metabolism, the aim of the present study was to evaluate serum Klotho, FGF-23, and 25-hydroxy Vit D levels in the scleroderma patients compared with the healthy controls." (PMID 28540270, 2017). "The purpose of this study was to evaluate serum Klotho, FGF-23, intact PTH (iPTH) and vitamin D levels in scleroderma patients compared with the healthy controls." (PMID 28540270, 2017). "Patients with SSc are characterized by lower Klotho concentration; however, the role of this finding remains obscure, as, in studies, Klotho was neither correlated with disease severity nor scleroderma-related damage." (PMID 30562918, 2018).
systemic lupus erythematosus (3 papers, 2017 to 2025). An autoimmune multi-organ disease typically associated with vasculopathy and autoantibody production. "The use of soluble klotho as a biomarker has been investigated in systemic lupus erythematosus (SLE), and more recently, its proangiogenic effect has been tested in a wound healing assay using human SSc-derived microvascular endothelial cells." (PMID 28912623, 2017). "Systemic lupus erythematosus (SLE) patients treated with prednisone had higher circulating Klotho." (PMID 39272986, 2024).